GPX4 (glutathione peroxidase 4)
Diseases named in the same sentence as GPX4 in open-access papers (continued):
Sharing a sentence is not in itself a finding about the gene and the disease.
Obesity (continued). "Taken together, our findings establish macrophage GPX4 as a key regulator of metabolic inflammation, lipid homeostasis, and insulin sensitivity in the context of obesity." (PMID 41524084, 2026). "The results showed that macrophage‐specific deletion of Gpx4 attenuated HFD‐induced obesity and improved insulin sensitivity in mice in vivo." (PMID 41524084, 2026). "Our findings identify macrophage GPX4 as a key mediator of obesity‐induced insulin resistance and metabolic malfunction." (PMID 41524084, 2026). "Mice with macrophage‐specific Gpx4 deletion (Gpx4Mac‐KO) were protected against HFD‐induced obesity and insulin resistance." (PMID 41524084, 2026). "We demonstrate that efficacy of ICI and dependence on GPX4 are promoted by obesity, but that these approaches behave antagonistically in combination." (PMID 40001204, 2025). "We conclude that GPX4 and PC expression are inversely related in TNBC cells, and GPX4 and obesity interact to impact TNBC progression and treatment responses." (PMID 40001204, 2025). "Our findings revealed a significant increase in the expression of Gpx4, a key enzyme involved in regulating lipid peroxidation, following the SH treatment in both diet-induced obesity (DIO) mouse and primary SVF cells." (PMID 39334717, 2024). "Common mechanisms of ferroptosis including iron overload, lipid peroxidation, GPX4 inhibition, and system Xc− inhibition in obesity, which lead to decrease of GSH, increased ROS, and even ferroptosis." (PMID 39396974, 2024). "In this study, we investigated the effectiveness of oral carnosine supplementation in mitigating the structural and functional changes in the heart that are known to accompany obesity in both wild-type (WT) and GPx4+/− mice." (PMID 38348353, 2023). "Recent genetic and epidemiological studies showed that reduced Gpx4 levels or reduced catalytic activity led to obesity, cardiovascular disease, and inflammation." (PMID 35186168, 2022). "Gpx4 haploinsufficient (GPx4+/−) mice fed diet-induced obesity exhibited glucose intolerance, dyslipidemia, cardiac hypertrophy and fibrosis as a consequence of significant increases in lipid peroxide-derived aldehydes." (PMID 35740085, 2022). "The expression of GPx4 was primarily located in the microvillous membrane of placentas, and lower signal was observed in placentas from the group with pBMI suggestive of obesity than in the group with normal weight." (PMID 31312657, 2019). "Placental GPx4 expression was lower in the group with pBMI suggestive of obesity than in the normal weight group (ß = -0.08, p = 0.03, adjusted for gestational age and magnesium intake)." (PMID 31312657, 2019). "However, the specific role of macrophage‐derived GPX4 in obesity‐induced insulin resistance remains largely undefined." (PMID 41524084, 2026). "Additionally, obesity activates the GPX4-dependent ferroptosis signaling pathway in epididymal adipose tissue during SAP." (PMID 40331957, 2025). "In our study, suppression of GPX4 heightened MDSC levels above that of obesity alone." (PMID 40001204, 2025). "In summary, the regulation of iron levels and GPX4 may represent potential therapeutic targets for managing obesity in clinical settings." (PMID 38260171, 2023). "Interestingly, GGPP alone exhibited a significant increase in the level of GPX4, which is likely related to obesity-reduced GPX4 in HFD mice." (PMID 36297049, 2022). "And studies have described that impaired GPX4 activity is associated with obesity, although the biological consequences have not yet been determined." (PMID 36479119, 2022). "Importantly, both loci showed protection against obesity: GPX3 rs922429 T allele and GPX4 rs2074451 T allele." (PMID 32752212, 2020). "In addition, polymorphisms rs757228 and rs8103188 of GPX4 (negatively), as well as variants rs445870 of GPX5 and rs406113 of GPX6 (positively), were associated with obesity in prepubertal Spanish children." (PMID 32344656, 2020).
Obesity (continued). "In addition, two SNPs, GPX3 rs922429 and GPX4 rs2074451 showed protection against obesity classified by BFP." (PMID 32752212, 2020). "In addition, we found two polymorphisms the GPX4 rs2074451 and GPX3 rs922429 significantly and marginally associated with obesity by PBF respectively." (PMID 32752212, 2020). "In addition, we identified a protective effect of SNPs in GPX3 rs922429 and GPX4 rs2074451 in Mexican children and adolescents, only when obesity was defined under the BFP criterion instead of BMI." (PMID 32752212, 2020). "In this study, we report a decrease in GPx4 associated with prepregnancy obesity in noncomplicated pregnancies." (PMID 31312657, 2019). "A decreased expression of GPx4 in placentas of women with prepregnancy obesity could result in greater exposure of the product to OS." (PMID 31312657, 2019). "On the immune side, obesity may cause M2 macrophages ferroptosis due to damage to iron-rich ATMs (MFehi) and antioxidant ATMs (Mox), and lead to Treg cells ferroptosis through reductions in NRF2, GPX4, and GCH1 levels." (PMID 36479119, 2022). "This process is amplified by downregulation of GPX4 and FSP1 in MAFLD:GPX4 inhibition: Obesity-induced hyperinsulinemia activates mTORC1, which suppresses NRF2-mediated GPX4 transcription." (PMID 40689204, 2025). "This work establishes a diet-dependent effect of GPX4 suppression in primary TNBC tumor growth and identifies a promising new anticancer target for breaking obesity-TNBC links." (PMID 40001204, 2025). "It is noteworthy that Fer-1 treatment mitigated the effects of obesity-induced GPX4 expression.Fer-1 reduced iron buildup and lipid peroxidation in HFD-fed mice while increasing SLC7A11 and GPX4 expression." (PMID 38260171, 2023). "Carboplatin treatment was highly effective at reducing tumor growth regardless of GPX4 or obesity status (p < 0.01, each comparison), while GPX4 knockdown modestly reduced tumor progression in both nonobese and DIO mice." (PMID 40001204, 2025). "Our findings identify GPX4 as a critical regulator of in vivo tumor progression specifically in the context of DIO, delineating a previously unknown relationship between obesity and TNBC metabolism." (PMID 40001204, 2025). "We establish that in TNBC tumors from obese mice, GPX4-mediated redox defense is a targetable vulnerability, and that GPX4 is a powerful regulator of treatment response in our metM-Wntlung model of TNBC and obesity." (PMID 40001204, 2025). "Moreover, GPX4-mediated redox defense, alone or in combination with chemotherapy, is a targetable vulnerability for treating TNBC, including obesity-related TNBC." (PMID 40001204, 2025). "We conclude that GPX4-mediated redox defense, alone or in combination with therapies such as carboplatin, is an actionable target for treatment of TNBC, particularly in patients with obesity." (PMID 40001204, 2025). "Although the GPX4 rs713041 [C/T] variant, located in the 3’UTR, the mRNA region important for selenocysteine insertion, was not investigated with obesity, this polymorphism showed risk modulation for diabetic retinopathy and cardiovascular autonomic neuropathy in patients with type 1 diabetes." (PMID 33924357, 2021). "Recent research found that GPX4 was reduced in HFpEF mice with obesity and impaired glucose tolerance, and imeglimin treatment not only improved their abnormal systemic glucose metabolism and visceral obesity, but also suppressed the upregulation of iNOS and restored expression of Xbp1s and GPX4." (PMID 36139417, 2022). "GPX4 suppression, alone or with current TNBC therapies, impacts outcomes in preclinical TNBC models with or without obesity and offers a new, plausible mechanistic target for TNBC treatment." (PMID 40001204, 2025). "It has been demonstrated that obesity up-regulates hepatic expressions of MSRB1, SELENON, -P, and -W, as well as GPX4 in diabetic patients by 33–50%, as compared to non-obese examinees." (PMID 32344656, 2020).
Obesity (continued). "GPX4 expression in tumors correlates with lower response to immunotherapy treatments (Supplementary 3 A-B), and GPX4 inhibition synergizes with immune checkpoint inhibitors to reduce tumor burden in models of TNBC without obesity." (PMID 40001204, 2025). "In summary, although the two neurons did not die of GPX4 reduction, the study focused on only one point of GPX4 and did not delve into other regulators, indicating that there are other pathways affecting the activity of POMC neurons under obesity conditions." (PMID 36479119, 2022).
diabetic nephropathy (25 papers, 2021 to 2026). "Moreover, reduced GPX4 levels were associated with the severity of diabetic kidney disease and an increased risk of progression to end-stage renal disease." (PMID 37361521, 2023). "Hederagenin inhibits ferroptosis induced by the TGF-β/Smad3 signaling pathway in renal tubular cells by reducing NOX4 expression and increasing GPX4 expression, thereby improving fibrosis in diabetic nephropathy mouse models." (PMID 39857243, 2024). "In diabetic nephropathy models, inhibiting GPX4 ubiquitination reduces oxidative stress, slows ferroptosis, and improves kidney function." (PMID 39857243, 2024). "A number of studies have shown that the expression of GPX4 is significantly lower in kidney biopsy samples from patients with diabetic kidney disease." (PMID 37361521, 2023). "A novel identified circular RNA, mmu_mmu_circRNA_0000309 involves in Germacrone-mediated the improvement of diabetic nephropathy through regulating ferroptosis by targeting miR-188–3p/GPX4 signaling axis." (PMID 38076182, 2023). "This is the first report that PD has a protective effect on diabetic nephropathy, possibly through inhibition of GPX4-mediated ferroptosis." (PMID 38076182, 2023). "Our findings of high circulating levels of sTfR1 together with low levels of GPX4 are consistent with the hypothesis that ferroptosis may be over-activated in COPD, similar to what has been reported for ferroptosis associated with diabetic nephropathy." (PMID 40542968, 2025). "Alleviating diabetic nephropathy by attenuated ferroptosis via activating GPX4." (PMID 40568564, 2025). "Notably, non-coding RNA was reported to play a role in podocyte injury in diabetic nephropathy through regulating ferroptosis by targeting miR-188-3p/GPX4 signaling Axis." (PMID 37819479, 2023). "Therefore, molecules on the Nrf2/HO-1/GPX4 pathway may be promising intervention targets for the treatment of diabetic nephropathy." (PMID 38076182, 2023). "A prospective observational study indicated that combining GPX4, ACSL4, MDA, and ROS could effectively predict diabetic nephropathy." (PMID 41198625, 2025). "In diabetic nephropathy renal biopsies, ferroptosis-related molecules SlC7A11 and GPX4 expression were reduced compared to in non-DN patients." (PMID 36432138, 2022). "The present study have found that serum ferroptosis markers GPX4 and ACSL4 as well as iron metabolism indexes are closely related to the severity of renal disease in type 2 diabetic patients, which may become biomarkers for diagnosis and treatment monitoring of diabetic nephropathy in the future." (PMID 38189040, 2023).
Parkinson disease (25 papers, 2011 to 2026). A progressive degenerative disorder of the central nervous system characterized by loss of dopamine producing neurons in the substantia nigra and the presence of Lewy bodies in the substantia nigra and locus coeruleus. "In Parkinson’s disease, dopamine oxidation promotes GPX4 ubiquitination and loss, provoking dopaminergic neuron ferroptosis; restoring GPX4 ameliorates degeneration and motor deficits." (PMID 41190075, 2025). "Preserved GPX4 activity is critical for preventing ferroptosis, which is implicated in Parkinson’s disease and cancer progression." (PMID 40276370, 2025). "As a key antioxidant axis, the NRF2/HO-1/GPX4 pathway not only protects against skin aging and damage caused by ultraviolet radiation but also plays a broad role in diseases such as Parkinson’s disease, periodontitis, and non-alcoholic fatty liver disease." (PMID 40143123, 2025). "Motor behavioral assays revealed that GPX4 deficiency in substantia nigra significantly accelerated parkinsonism progression in A53T mice." (PMID 37183824, 2023). "This study demonstrates an up-regulation of GPX4 in neurons of substantia nigra and association of this protein with dystrophic axons in striatum of Parkinson's brain, indicating a possible neuroprotective role." (PMID 21255396, 2011). "Oxidation of DJ-1 is associated with an increase in cerebral cortex of GPX4 in subjects with sporadic Parkinson's disease." (PMID 21255396, 2011). "These phenotypes of dopaminergic neuronal dysfunction might be associated with the activation of ferroptosis and triggered by the insufficiency of GPX4 during synucleinopathy-associated parkinsonism." (PMID 37183824, 2023). "In Parkinson’s disease, altered GPx-4 expression and distribution has been associated with pathological changes in the brains of patients, supporting the idea that high GPx-4 levels could protect neurons against oxidative damage." (PMID 37761814, 2023). "Therefore, the depletion of dopamine in the brain of individuals with Parkinson’s disease (PD) may lead to ferroptosis due to the loss of GPX4." (PMID 38671843, 2024). "Evidence for ferroptosis activity, including increased LPO, increased iron stores, decreased GPX4, and decreased glutathione, is present in several CNS diseases, such as Alzheimer’s disease and Parkinson’s disease." (PMID 40227266, 2025). "This phenomenon, similar to what has been proposed in Parkinson’s disease, suggests a compensatory mechanism where cells increase transcription to compensate for reduced GPX4 protein levels." (PMID 39468028, 2024). "Keyword analysis highlights the critical role of ferroptosis in the pathogenesis of Parkinson’s disease, identifying GPX4 as a key enzyme mitigating lipid peroxidation." (PMID 39280701, 2024). "Overall GPX4 was significantly reduced in substantia nigra in Parkinson's vs. control subjects, but was increased relative to the cell density of surviving nigral cells." (PMID 21255396, 2011). "In both control and Parkinson's samples, GPX4 was found in dopaminergic nigral neurons colocalized with neuromelanin." (PMID 21255396, 2011). "For example, activation of the STAT3/HIF1α axis promoted α-synuclein-induced ferroptosis, with GPX4 suppression and iron dyshomeostasis in a Parkinson’s disease model, whereas pharmacological STAT3 inhibition reduced lipid ROS and iron accumulation in microglia." (PMID 41304754, 2025). "For instance, dopamine quinone (DAQ) and α-synuclein facilitate neural precursor cell expressed developmentally down-regulated protein 4 (NEDD4)-mediated GPX4 ubiquitin-proteasome degradation, thereby promoting ferroptosis in neurons during Parkinson’s disease (PD)." (PMID 39856053, 2025). "Alternatively, GPX4 might be degraded by the ubiquitin proteasome system due to its oxidation, as observed in experimental mouse model for Parkinson’s disease." (PMID 37542104, 2023). "GPX4 replenishment alleviates synucleinopathy and parkinsonism." (PMID 37183824, 2023).
Parkinson disease (continued). "SNCAA53T/Gpx4+/fl double transgenic mice were bilaterally injected with adeno-associated virus–mediated (AAV-mediated) Cre recombinase constructs into the substantia nigra, to conditionally knockdown Gpx4 expression (A53T/Gpx4 CKD) before the onset of typical parkinsonism." (PMID 37183824, 2023). "Similarly, research has indicated that the reduction in glutathione peroxidase 4 (GPX4) expression and system xc activity in the substantia nigra of Parkinson's disease patients contributes to iron-induced cell death." (PMID 40488714, 2025). "Given that ACSL4 and GPX4 are pivotal regulators of ferroptosis, lncRNA NEAT1 might modulate ferroptosis via these molecules, presenting a promising therapeutic approach for Parkinson’s disease." (PMID 39280701, 2024). "Further, substantia nigra–specific Gpx4 knockdown induced lipid peroxidation and triggered typical parkinsonism, even in the absence of α-synuclein oligomers." (PMID 37183824, 2023). "To investigate a possible role of the phospholipid hydroperoxidase glutathione peroxidase 4 (GPX4) in protection from oxidative stress, we investigated GPX4 expression in postmortem human brain tissue from individuals with and without Parkinson's disease." (PMID 21255396, 2011). "In putamen, GPX4 was concentrated within dystrophic dopaminergic axons in Parkinson's subjects, although overall levels of GPX4 were not significantly different compared to control putamen." (PMID 21255396, 2011).